MIR6880 (microRNA 6880)
Synonyms: hsa-mir-6880
Gene: MicroRNA gene on chromosome 12 (124,337,181 to 124,337,242, reverse strand). Ensembl gene ENSG00000275967.
Homologues: Orthologues: chimpanzee MIR6880 (100% identical).